MTOR (mechanistic target of rapamycin kinase)
Diseases named in the same sentence as MTOR in open-access papers (continued):
Sharing a sentence is not in itself a finding about the gene and the disease.
chondrosarcoma (continued). "However, prolonged stable disease was achieved for chondrosarcoma patients by combining mTOR inhibitors with liposomal doxorubicin or EGFR, IGF1R, VEGF inhibitors." (PMID 33425984, 2020). "Moreover, for sapanisertib (mTOR inhibitor) treatment, a recovery in chondrosarcoma growth, previously observed in mice models, was also observed using long-term treatment." (PMID 33425984, 2020). "To determine whether mTOR is activated in HEMC-SS chondrosarcoma cells and whether this is associated with EGFR activation, we analyzed mTOR phosphorylation status in the absence and presence of the EGFR inhibitor, AG1478." (PMID 31139331, 2019). "Aberrant activation of oncogenic signals, ERK1/2 and AKT/mTOR in chondrosarcomas may sustain cell proliferation and survival." (PMID 31139331, 2019). "Several signaling pathways, such as hedgehog, non-receptor tyrosine kinase (Src), phosphatidylinositol-4,5-bisphosphate 3-kinase (PI3K)/serine/threonine-protein kinase (AKT)/mammalian target of rapamycin (mTOR), and angiogenesis are suggested to play an important role in chondrosarcoma." (PMID 29546033, 2018). "Thus, while the induction of apoptosis is very limited, metformin and phenformin decreased mTOR activity in chondrosarcoma cells, and metformin decreased autophagy, an effect that is counteracted by chloroquine." (PMID 29576625, 2018). "Thus, our results show that BDNF promotes VEGF-C expression and lymphangiogenesis in human chondrosarcoma cells via the MEK/ERK/mTOR signaling pathway." (PMID 28771226, 2017). "We further explored whether PI3K, Akt, and mTOR signals were involved in adiponectin-induced HIF-1α activation in human chondrosarcoma cells." (PMID 26468982, 2015). "Based on these data and on studies showing additive effects of mTOR inhibitor with chemotherapy, the antitumor effect of a combination of chemotherapy and/or everolimus, an mTOR inhibitor was tested in a preclinical rat chondrosarcoma model." (PMID 22761648, 2012). "Taken together, our preclinical data indicate that mTOR inhibitor may be effective as a single agent in treating chondrosarcoma patients." (PMID 22761648, 2012). "Thus, the Saos-2 and chondrosarcoma cells overexpressed miRNAs that potentially inhibit mTOR signalling." (PMID 21437224, 2011). "Therefore, restoring miR-100 expression could be a potential therapeutic approach to prevent chondrosarcoma progression by suppressing aberrant activation of the mTOR pathway." (PMID 38542153, 2024). "For example, ZNF704 acts as an oncogene in BC, chondrosarcoma, and uveal melanoma by regulating circadian rhythm and AKT/mTOR signaling." (PMID 38429817, 2024). "Our results indicate that visfatin inhibits miR-1264 production through the PI3K/Akt/mTOR signaling cascade, and thereby promotes PDGF-C expression and chondrosarcoma angiogenesis." (PMID 36359873, 2022). "Our study revealed that visfatin increased PDGF-C expression and activated PI3K/Akt/mTOR signaling in chondrosarcoma cells, which subsequently downregulated levels of miR-1264 expression and promoted PDGF-C expression and angiogenesis in chondrosarcoma tumors." (PMID 36359873, 2022). "It appears that visfatin-induced activation of PI3K, Akt, and mTOR signaling cascade controls visfatin-enhanced PDGF-C synthesis and promotes chondrosarcoma angiogenesis." (PMID 36359873, 2022). "This study has shown that visfatin enhances PDGF-C synthesis in human chondrosarcoma cells and facilitates EPC angiogenesis via PI3K/Akt/mTOR signaling." (PMID 36359873, 2022). "The mTOR/PI3K pathway as well as IGFR-1 have been studied as a therapeutic anticancer target and this work has served as a foundation for studies in chondrosarcoma." (PMID 34938658, 2021). "In conclusion, our study has identified that NGF promotes LOX-dependent migratory and invasive activities in human chondrosarcoma cells by suppressing miR-149-5p synthesis via the PI3K, Akt, and mTOR signaling cascades." (PMID 34815382, 2021).
chondrosarcoma (continued). "We also confirmed that NGF facilitates LOX-dependent chondrosarcoma cell migration and metastasis by suppressing miR-149-5p synthesis via PI3K, Akt, and mTOR signaling." (PMID 34815382, 2021). "PI3K and Akt inhibitors also inhibited NGF-promoted phosphorylation of mTOR, indicating that PI3K/Akt-dependent mTOR activation mediates NGF-facilitated promotion of LOX synthesis and chondrosarcoma cell motility." (PMID 34815382, 2021). "Baicalin was demonstrated to have cytotoxic and antitumor effects in human chondrosarcoma through inducing apoptotic death and downregulating the phosphoinositide 3-kinase (PI3K)/Akt/mTOR pathway." (PMID 33585556, 2020). "We also found that mTOR phosphorylation in chondrosarcoma cells was increased after CCN6 treatment, while incubation of cells with PI3K or Akt inhibitors antagonized CCN6-induced mTOR phosphorylation." (PMID 30237403, 2018). "The dual inhibition of the PI3K/Akt/mTOR and RAF/MEK/ERK signaling pathways has also been demonstrated to have synergistic antiproliferative effects in chondrosarcoma cells." (PMID 30586948, 2018). "Our results indicate that endogenous CCN6 activates the PI3K/Akt/mTOR/NF-κB signaling pathway and augments MMP-9-dependent lung metastasis of chondrosarcoma in vivo." (PMID 30237403, 2018). "This indicates that the PI3K/Akt/mTOR signaling pathway is required for CCN6-induced MMP-9 expression and chondrosarcoma cell metastasis." (PMID 30237403, 2018). "In this current study, stimulation of chondrosarcoma cell lines with CCN6 promoted cell motility and MMP-9 expression, which in turn activated the PI3K/Akt/mTOR/NF-κB signaling pathway." (PMID 30237403, 2018). "We found that an mTOR inhibitor (rapamycin) and siRNA both abolished BDNF-induced VEGF-C expression in chondrosarcoma cells." (PMID 28771226, 2017). "In recent studies, researchers have found that PI3K/AKT/mTOR and HIF-1α pathway has been involved in the VEGF-A-dependent angiogenesis in human chondrosarcoma induced by adiponectin." (PMID 26958938, 2016). "Our recent study demonstrated that adiponectin promoted angiogenesis in human chondrosarcomas through adiponectin receptors and the PI3K/Akt/mTOR/HIF signaling pathway." (PMID 26712749, 2015). "Here we found that adiponectin induced VEGF-A expression and subsequently promoted angiogenesis and tumor growth in human chondrosarcoma cells through the activation of AdipoR1/R2 receptor, PI3K, Akt, mTOR, and HIF-1α signaling pathways." (PMID 26468982, 2015). "Here we reported that adiponectin promotes VEGF-A expression in human chondrosarcoma via activation of phosphoinositide 3 kinase (PI3K), Akt, mammalian target of rapamycin (mTOR), and hypoxia-inducible factor-1α (HIF)-1α signaling pathways." (PMID 26468982, 2015). "These suggest that AdipoR/PI3K/Akt/mTOR/HIF-1α is a common pathway responsible for VEGF-A expression and angiogenesis in chondrosarcoma cells." (PMID 26468982, 2015). "We also sought to determine whether LOX mediates NGF-induced migration and invasion abilities of chondrosarcoma cells, and whether this process is regulated by PI3K, Akt, and mTOR signaling." (PMID 34815382, 2021). "In clinic, no significant single-agent mTOR treatment effect has been observed in chondrosarcoma patients thus far." (PMID 33425984, 2020). "A phase II study using ridaforolimus, another mTOR inhibitor, as a single agent did not have a noted effect on chondrosarcoma patients in the cohort." (PMID 33425984, 2020). "Additionally, dual PI3K/mTOR inhibitor BEZ235 inhibited mouse xenograft chondrosarcoma cell lines JJ012 in vitro and in vivo, prompting more interest in the mTOR pathway in chondrosarcoma treatment." (PMID 32707689, 2020). "Indeed, treatment of chondrosarcoma cells with AG1478 inhibits the phosphorylation of EGFR receptor and of ERK1/2 and AKT/mTOR." (PMID 31139331, 2019).
chondrosarcoma (continued). "Interestingly, inhibition of EGFR following treatment with AG1478 markedly decreased the activation of mTOR, therefore suggesting that EGFR mediates the activation AKT/mTOR signaling pathways in HEMC-SS chondrosarcoma cells." (PMID 31139331, 2019). "Thus, the PI3K/Akt/mTOR signaling pathway must be activated for CCN6-induced enhancement of cell migration, invasion, and MMP-9 production in human chondrosarcoma cells." (PMID 30237403, 2018). "Indeed, we observed that p85, Akt, and mTOR siRNAs reduced MMP-9 expression, and inhibited chondrosarcoma cells migration and invasion." (PMID 30237403, 2018). "Our study revealed that the GABAB receptor antagonist had anti-tumor effects in OUMS-27 cells, a high-grade chondrosarcoma cell line, through cell cycle arrest at G1/S phase and induced apoptosis via dual inhibition of the PI3/Akt/mTOR and MAPK signaling pathways." (PMID 29514603, 2018). "Treating chondrosarcoma with PI3K, Akt, and mTOR inhibitors reversed NGF-promoted inhibition of miR-149-5p expression, which suggests that NGF may increase LOX expression and chondrosarcoma metastasis by inhibiting miR-149-5p synthesis via the PI3K, Akt, and mTOR signaling cascades." (PMID 34815382, 2021). "Targeting IDH mutations, lipid, glucose and mitochondrial metabolic targets, hedgehog, PI3K/Akt/MTOR, HIF and SRC pathways have yielded mixed results in clinical studies without clear therapeutic options in chondrosarcoma." (PMID 34938658, 2021).
endothelial dysfunction (41 papers, 2011 to 2025). In vascular diseases, endothelial dysfunction is a systemic pathological state of the endothelium (the inner lining of blood vessels) and can be broadly defined as an imbalance between vasodilating and vasoconstricting substances produced by (or acting on) the endothelium. "We examine mechanistic pathways including NF-κB, AMPK, PI3K/Akt/mTOR, and Nrf2, which are implicated in chronic inflammation, endothelial dysfunction, and muscle wasting." (PMID 40732928, 2025). "Normally, high glucose/fat stress can trigger autophagy and also cause endothelial dysfunction; by activating Akt and mTOR, naringin signaled the cells to reduce autophagic flux, which preserved endothelial cell integrity and function." (PMID 40871686, 2025). "It has been found that Huangbai can improve chronic inflammatory injury caused by endothelial dysfunction by regulating the PI3K-Akt-mTOR signaling pathway." (PMID 38902425, 2024). "Silica nanoparticles evoke an inflammatory response and endothelial dysfunction associated with the activation of the PI3K/Akt/mTOR pathway." (PMID 28420166, 2017). "Thus, it is likely that loss of MTOR can cause endothelial dysfunction in part by promoting autophagy." (PMID 39510184, 2024). "Given the association between antiphospholipid antibodies, endothelial dysfunction, and intimal hyperplasia, the use of sirolimus-eluting stents or balloons targeting the mTOR pathway may offer a promising strategy for aPL+ patients." (PMID 39830377, 2024). "A possible explanation could be the expression of transcription factors, such as serum response factor (SRF) and mammalian target of rapamycin (mTOR), which are critical regulators in vascular ECs and are associated with endothelial dysfunction." (PMID 33317046, 2020). "Our results indicate that increased mTOR activation may underlie vascular oxidative stress, endothelial dysfunction, increases in large elastic artery stiffness, and structural adaptations in the vessel wall with advancing age." (PMID 27660040, 2017). "A study found that in endothelial cells exposed to high glucose and fat (simulating diabetic/hyperlipidemic stress), naringin inhibited overactive autophagy via the PI3K-Akt-mTOR pathway, thereby ameliorating endothelial dysfunction." (PMID 40871686, 2025). "Accumulating evidence indicates that mTOR plays a central role in endothelial dysfunction, autophagy inhibition, inflammation amplification, and pregnancy failure in APS." (PMID 41438739, 2025). "Key regulatory pathways—including PDGF-BB, TGF-β, MAPK, mTOR, and NF-κB—as well as non-coding RNAs, orchestrate this process in response to endothelial dysfunction, inflammatory activation, and altered hemodynamics." (PMID 41584287, 2025). "CaD improved the endothelial dysfunction and inflammation caused by high glucose, and restored autophagy by inhibiting the VEGF/PI3K/AKT/mTOR signaling pathway." (PMID 41168780, 2025). "Similar changes in the expression of miR-22-3p, Phf8, mTOR- and autophagy-related proteins/mRNAs were also found in vivo in hearts of severely HHcy Cbs−/− mice, which show endothelial dysfunction." (PMID 39859460, 2025). "Among the autophagic pathways described in EC, the serine/threonine kinase mTOR (mammalian target of rapamycin) is activated by low pathological shear stress, leading to inhibition of autophagy and subsequently to endothelial dysfunction." (PMID 40445729, 2025). "mTOR modulates the response to oxidative stress in endothelial cells, contributing to endothelial dysfunction, a key early event in CAD." (PMID 40734978, 2025). "This process involves endothelial dysfunction and the activation of the mTOR signaling pathway, which plays a central role in vascular remodeling and intimal hyperplasia—key processes in restenosis." (PMID 39830377, 2024). "The pathophysiology of stenotic lesions in APS involves endothelial dysfunction and activation of the mammalian target of rapamycin (mTOR) pathway." (PMID 39830377, 2024).
endothelial dysfunction (continued). "One proposed mechanism for endothelial dysfunction with chronically elevated mTOR is a disruption of endothelial nitric oxide signaling." (PMID 39234308, 2024). "Collectively, these results suggest that elevated mTOR signaling contributes to endothelial dysfunction in SLE which can be prevented by treating with rapamycin." (PMID 39234308, 2024). "Activation of mTOR/S6K1 signaling has been demonstrated to play a causal role in endothelial senescence and endothelial dysfunction related to eNOS uncoupling in both a cell culture model and a rat aging model." (PMID 37894840, 2023). "Evidence has demonstrated that mTOR signaling is augmented in arteries from older mice which display endothelial dysfunction." (PMID 37894840, 2023). "Lifelong caloric restriction prevents augmented arterial mTOR signaling and endothelial dysfunction." (PMID 37894840, 2023). "Additional pathways, such as extracellular matrix (ECM) receptor interaction, focal adhesion, regulation of actin cytoskeleton, and mammalian target of rapamycin (mTOR), are known to be involved in endothelial dysfunction." (PMID 36232660, 2022). "Rapamycin acts as an inhibitor of the mTOR pathway that is characterized by increased EC senescence and endothelial dysfunction." (PMID 33801956, 2021). "The enhancement of the mTOR pathway that is characteristic of ageing leads to increased endothelial cell senescence and endothelial dysfunction." (PMID 33801956, 2021). "Remarkably enriched KEGG pathways are mTOR, FoxO, and MAPK pathways, and they are known to play an essential role in endothelial dysfunction, causing inflammation and proliferation of the tunica intima." (PMID 32148949, 2020). "In this study, we used an established mouse model of arterial aging to assess the role of mTOR activity in endothelial dysfunction and large artery stiffening with advancing age." (PMID 27660040, 2017). "Additionally, mTOR regulates endothelial autophagy; anti-phospholipid antibody complexes inhibit autophagy via the PI3K/AKT/mTOR pathway, causing endothelial dysfunction and oxidative stress, which exacerbate vascular damage and inflammation in APS." (PMID 41438739, 2025). "Additionally, hyperphosphorylation of mTOR effectors exacerbates endothelial dysfunction, increasing oxidative stress and apoptosis." (PMID 40734978, 2025). "Impaired mTOR signaling in kidney blood vessels may lead to endothelial dysfunction, increasing vascular resistance." (PMID 39513878, 2024). "Furthermore, mTOR has been reported to exert a protective effect against oxidative injury-induced endothelial dysfunction and cardiomyocyte toxicity." (PMID 38370014, 2024). "The relationship between mTOR and endothelial dysfunction is well documented." (PMID 32907629, 2020). "However, it is plausible that the BPLPL-PLLA nanoparticles may have upregulated oxidative stress within the cells that can activate autophagy and eventually lead to endothelial dysfunction via the PI3K/Akt/mTOR pathway as seen for silica NPs." (PMID 31824940, 2019). "However, elevated levels of mTOR were not directly related to endothelial dysfunction in obesity, which points to a discrepancy between pathologically and experimentally induced mTORC1 activity on endothelial function." (PMID 39234308, 2024). "Therefore, inhibition of FDPS ameliorates endothelial dysfunction, such as inhibition of abnormal proliferation, in PAH, in part due to a reduction in GTP-bound active Rac1 and accompanying reduced autophagy via the PI3K/AKT/mTOR signaling pathway." (PMID 35962329, 2022).
endothelial dysfunction (continued). "Additionally, it prevents endothelial dysfunction by upregulating the eNOS expression and improves the balance between apoptosis and autophagy; ginsenoside Rg1 has also been reported to inhibit AS by activating the AMPK/mTOR signaling pathway in the macrophages." (PMID 34873408, 2021). "Although the role of mTOR/S6K1 in regulation of lifespan of various organisms and animal models has been well documented, it is, however, not known whether mTOR, particularly S6K1, is involved in vascular endothelial aging and associated endothelial dysfunction." (PMID 21544240, 2011).